JMJD7-PLA2G4B (JMJD7-PLA2G4B readthrough)
Synonyms: HsT16992; cPLA2-beta
Gene: Protein-coding gene on chromosome 15 (41,828,095 to 41,848,155, forward strand). Ensembl gene ENSG00000168970.
Genetic constraint (gnomAD): Loss-of-function variants: 153 observed, 124.49 expected, observed/expected ratio (o/e) 1.23, 90% interval 1.08 to 1.4. The synonymous counts are far from expectation, so gnomAD's model fits this gene poorly and the ratio says little. Missense variants: 1,514 observed, 1,314.8 expected, observed/expected ratio (o/e) 1.15, 90% interval 1.1 to 1.2. Synonymous variants: 674 observed, 557.39 expected, observed/expected ratio (o/e) 1.21, 90% interval 1.13 to 1.29.